TCP11L1 (t-complex 11 like 1)
Synonyms: FLJ11336; dJ85M6.3
Tractability: PROTAC: ubiquitination databases record sites on it; its protein half-life has been measured.
Gene: Protein-coding gene on chromosome 11 (33,039,417 to 33,105,943, forward strand). Ensembl gene ENSG00000176148.
Subcellular location (Human Protein Atlas): Cytosol; Golgi apparatus
Gene Ontology:
Molecular function: protein binding
Biological process: signal transduction
Cellular component: microtubule
Genetic constraint (gnomAD): Loss-of-function variants: 29 observed, 52.28 expected, observed/expected ratio (o/e) 0.55, 90% interval 0.41 to 0.76. The upper end of that interval is the gene's LOEUF score, 0.76, which puts it in group 3 of 6, group 1 being the genes least tolerant of losing a copy. Missense variants: 480 observed, 619.2 expected, observed/expected ratio (o/e) 0.78, 90% interval 0.72 to 0.84. Synonymous variants: 198 observed, 235.79 expected, observed/expected ratio (o/e) 0.84, 90% interval 0.75 to 0.94.
Homologues: Orthologues: chimpanzee TCP11L1 (99% identical), macaque TCP11L1 (99% identical), dog TCP11L1 (88% identical), pig TCP11L1 (87% identical), rabbit TCP11L1 (85% identical), mouse Tcp11l1 (85% identical), rat Tcp11l1 (84% identical), guinea pig TCP11L1 (81% identical), tropical clawed frog tcp11l1 (58% identical), zebrafish tcp11l1 (53% identical), Drosophila melanogaster CG16721 (31% identical), Caenorhabditis elegans M05D6.2 (28% identical). Paralogues in human: TCP11L2 (43% identical), TCP11 (38% identical), TCP11X1 (36% identical), TCP11X2 (36% identical).
Diseases named in the same sentence as TCP11L1 in open-access papers:
TCP11L1 is named in the same sentence as 4 diseases in open-access papers, as found by Europe PMC text mining. Sharing a sentence is not in itself a finding about the gene and the disease. The quoted sentences say what the papers report.
Abdominal obesity (1 paper, 2019). Excessive fat around the stomach and abdomen. "The top four CpGs that were found to be differentially methylated between individuals with and without abdominal obesity were located at the genes c13orf36, ZC3H12D, MYO9B, and KCNG3 in females; and JPH3, TCP11L1, and GRIK3 in males (one CpG had no annotated gene)." (PMID 31212707, 2019).
atherosclerosis (1 paper, 2019). A disease characterized by the build-up of fatty material and calcium deposition in the arterial wall resulting in partial or complete occlusion of the arterial lumen. "Other CpGs in the genes NOD2 and TCP11L1 have been linked to atherosclerosis, and in the TSNARE1 gene, with CRP." (PMID 31212707, 2019).
cryptorchidism (1 paper, 2021). The failure of one or both testes of a male fetus to descend from the abdomen into the scrotum during the late part of pregnancy. "Of the genes with UDT mammal-specific indels, T-complex 11 like 1 (TCP11L1) is involved in cryptorchidism." (PMID 33568072, 2021).
TCP11L1 also shares sentences with these, for which no sentence is quoted: Azoospermia (1 paper).